CD4 (CD4 molecule)
Diseases named in the same sentence as CD4 in open-access papers (continued):
Sharing a sentence is not in itself a finding about the gene and the disease.
COVID-19 (continued). "Therefore, strategies to better mimic the heterogeneity of multi-specific T cell immunity caused by the natural infection would be required to leverage the vital role of both CD8+ and CD4+T cell responses in reducing the impact of COVID-19 and potentially provoking long-term immune responses." (PMID 34249101, 2021). "Finally, although HIV infection did not significantly alter the functional and phenotypical profile of SARS-CoV-2–specific CD4+ T cells, in patients with aTB, the global SARS-CoV-2–specific CD4+ T cell pattern was significantly different compared with HIV-uninfected COVID-19 patients." (PMID 33945513, 2021). "Two unusual subtypes of CD4+ T cells called clonally expanded cytotoxic phenotype, and proliferative exhausted phenotype were associated with disease severity in multi-omics studies, while the polyfunctionality and cytotoxicity of CD8+ T cells were attenuated in severe COVID-19 patients." (PMID 34373739, 2021). "Thus, in this acute-care setting, CD4+T cell level may provide early prognostic information in patients with COVID-19." (PMID 33435865, 2021). "However, unlike Spike-specific CD4+ T cells that show a substantially higher magnitude over the cross-reactive T cells in unexposed donors, the non-spike specific memory CD4+ T cells are associated with a lesser increase after COVID-19." (PMID 33777028, 2021). "In patients with mild COVID-19, tissue-resident memory (TRM) CD8+ and CD4+ T helper-17 (Th17) cells are characterized by increasing (presumably antigen-driven) clonal expansion and strengthened effector functions, whereas their counterparts remain more naive/intermediate in critical COVID-19." (PMID 34471261, 2021). "Furthermore, critical COVID-19 patients showed the lowest activation of S protein-specific CD4+ T cells, while similar activation compared to patients with mild and severe symptoms was detected for CD4+ T cells directed to M or N viral protein." (PMID 34194438, 2021). "More recently, we analyzed the repertoire of CD4 T cells recognizing severe acute respiratory syndrome coronavirus 2 (SARS-CoV-2) in previously unexposed individuals due to the potential implications of preexisting immunity in the modulation of coronavirus disease 2019 (COVID-19) severity." (PMID 33789994, 2021). "Notably, all close contacts developed responses at lower frequencies than 4%, while 64 (71.11%) and 32 (35.56%) of the 90 COVID-19 patients developed marked responses at the frequencies of higher than 4% for IFNγ+CD4+ T cells and IFNγ+CD8+ T cells, respectively." (PMID 33741972, 2021). "Therefore, we measured the expression of perforin in CD4 T cells from COVID-19 patients." (PMID 33777054, 2021). "Thus, our data reveal that increased functional breadth of CD4+ T cell responses to S and N are associated with known risk factors for severe COVID-19 independent of the production of IFN-γ." (PMID 33621211, 2021). "In severe COVID-19 cases, CD4+ T and CD8+ T cell levels could be remarkably low." (PMID 34436124, 2021). "The frequency of CD4 +T cells targeted to the spike protein correlates with neutralizing antibody titers, which may suggest that the T-cell response might be different among COVID-19 patients with different disease severity." (PMID 33717166, 2021). "Moreover, COVID-19 patients had a lower CD4, CD8, and natural killer (NK) cell number (p < 0.01)." (PMID 33808205, 2021). "However, both S and NCAP-specific tp and S dp producing CD4+ T cells were significantly increased in seropositive and seronegative post COVID-19 patients compared to unexposed HC, providing evidence for specific T cell responses in Ab− post COVID-19." (PMID 34322120, 2021). "Thus, an increase in CD3+ CD4+ Th cells is positively correlated with the severity of COVID-19." (PMID 34976886, 2021).
COVID-19 (continued). "Recent reports have also found increased neutrophil counts and decreased lymphocyte counts associated with COVID-19 Lymphocytopenia could explain the effect of SARS-CoV-2 on T lymphocytes, mainly on CD4+ T cells and CD8+ T cells, resulting in a decrease in lymphocyte numbers and IFN-γ production." (PMID 33914805, 2021). "Thus, to define whether COVID-19 can promote M. tuberculosis reactivation, we compared the expression of HLA-DR on M. tuberculosis–specific CD4+ T cells in the different cohorts." (PMID 33945513, 2021). "One of the most challenging approaches is to identify T and B cell epitopes that are correlating with optimal CD4+ helper, CD8+ cytotoxic T cell and B cell responses and may be associated with clinically mild COVID-19 courses or even constitute potential vaccine candidates." (PMID 33807854, 2021). "Patients with severe COVID-19 show markedly reduced CD4+ and CD8+ T lymphocyte levels compared to patients with moderate COVID-19, and the blood of patients with both severe or moderate COVID-19 is deficient in CD4+ CD25+ CD127lo and CD45RA+ regulatory T lymphocytes." (PMID 34360684, 2021). "While the fraction of CD4+ memory T cells expressing the chemokine receptor CCR9, which is associated with trafficking to the small intestine, was similar between patients with COVID-19 and healthy controls, their absolute numbers in the circulation were significantly reduced." (PMID 33959123, 2021). "Indeed, it was demonstrated that binding and neutralizing antibody responses decay over the first four months post-infection with a similar decline in Spike-specific CD4+ and circulating T follicular helper frequencies in a cohort of patients who recovered from mild/moderate COVID-19." (PMID 33260801, 2020). "Taken together, consistent with previous research 2,5, the ESR, CRP, PT, IL6, lymphocyte count, GGT, Prealbumin and CD4 have important value in the diagnosis of COVID-19, and the decrease of GGT may be an important indicator for judging the intestinal dysfunction of patients." (PMID 32547309, 2020). "Our data thus provide novel insights into the kinetics of antibody and CD4 T cell responses as well as viral loads that are key to understanding the role of adaptive immunity in combating the virus during acute infection and provide leads for the timing of immune therapies for COVID-19." (PMID 33262993, 2020). "The significant increase of CD4+ central memory cells, both in COVID-19 X-ray (+) and COVID-19 X-ray (−), in relation to the control group, might indicate appearance of immune memory in patients with COVID-19 infection, regardless of the occurrence of changes in lungs." (PMID 33291439, 2020). "Recent studies have in fact identified presence of virus specific CD4+ T cells in most COVID-19 patients and the levels of these cells correlate with virus specific IgG, indicating helper CD4+ T cell response may have an important role in limiting this infection." (PMID 33133083, 2020). "However, a slight decrease in CD4+ T cells was observed in severe COVID-19 patients." (PMID 32943497, 2020). "Thus, we were not able to analyze the kinetics of CD8 T cells or other cytokine-producing CD4 T cell subsets in parallel to Abs, and the possible beneficial or detrimental role of these cells in viral clearance or the pathogenesis of COVID-19 will have to be resolved in future studies." (PMID 33262993, 2020). "As all patients are lymphopenic, the neutrophil-to-CD8+ T cell ratio, counts of CD4 and CD8 T cells, and cytokine IL-6 and IL-10 can be identified as the most powerful prognostic factors for the progression of disease from mild to severe CoV-2 infection." (PMID 32781571, 2020). "Thus, most COVID-19 vaccine efforts focus on the elicitation of neutralizing antibodies, with additional interest in elicitation of CD4+ or CD8+ T cells." (PMID 33010815, 2020). "Furthermore, CD4+ as well as CD8+ T cells of COVID-19 patients display an activated phenotype." (PMID 33154972, 2020).
COVID-19 (continued). "Indeed, a lower BTLA frequency in memory compared to naive subsets of CD8+ and CD4+ T cells could be detected in COVID-19 and malaria patients as well as healthy donors." (PMID 32983106, 2020). "The multivariable results also indicated that the log transferred CD4 count was negatively associated with the occurrence of COVID-19 (AOR=0.06, 95%: CI 0.01-0.30), while log transferred length from HIV diagnosis was positively associated with the occurrence of COVID-19 (AOR=1.12, 95% CI:1.05-1.19)." (PMID 32818208, 2020). "In addition, vaccination strategies that induce airway memory CD4+ T cells targeting conserved epitopes could be safer and have broader applicability in the context of COVID-19 and other respiratory virus epidemics." (PMID 33178193, 2020). "The numbers of CD4 + and CD8 + T cells were dramatically reduced in COVID-19 patients, especially in severe to critical patients, with an increase in the CD4 + :CD8 + ratio." (PMID 41611759, 2026). "We explored for the first time the possible association between pre-vaccination T lymphocyte subpopulations (CD3+CD56+, CD56+ NK, CD4+, CD4+CD3+CD56+ cells) and the antibody response to the COVID-19 vaccine." (PMID 41727501, 2026). "In hospitalised COVID-19 patients, an increased frequency of IL-2 producing CD4+CD45RO+ memory T cells was observed, indicating a persistent CD4+ T cell-mediated immune response." (PMID 40242761, 2025). "and others have reported prolonged and/or severe COVID-19 in patients with marked reductions in CD19+ B-cells and CD4+ T-cells, and an increased proportion of exhausted CD4+ T-cells following treatment with bendamustine combined with anti-CD20 antibodies." (PMID 41267982, 2025). "This lymphopenia is thought to result from the rapid depletion of peripheral T lymphocytes, including both CD4+ and CD8+ cells, during acute COVID-19, potentially due to their sequestration within target organs." (PMID 40506946, 2025). "In conclusion, PLWH were more likely to receive a COVID-19 vaccine, and vaccinated PLWH had higher CD4+ T cell counts and were more likely to be virally suppressed." (PMID 40432125, 2025). "We also examined the correlation between the concentration of sPD-1 and the expression of membrane-bound PD-1 on CD4+ and CD8+ T cells across all COVID-19 groups and in comparison with the control group." (PMID 40005306, 2025). "Serial testing of CD4+ T-lymphocytes, CD8+ T-lymphocytes, and their ratio in peripheral blood T-lymphocytes and their subpopulations in patients with COVID-19 helps us to understand the state of cellular immune function in patients." (PMID 40988875, 2025). "Concomitantly, we observed a pronounced reduction of naive CD4+ and CD8+ T cells 6 months after COVID-19, which further indicated shifts in the T cell compartment." (PMID 41310351, 2025). "Severe COVID-19 patients compared to mild cases had lower CD3+ T cells (count and percentage), CD4+ T cells (count and percentage), CD8+ T cells (count), and NK cells (count), but higher CD19+ B cells (percentage) at baseline (p < 0.05, all)." (PMID 41157669, 2025). "Significantly increased levels of circulating cMet+ memory CD4+ and CD8+ T cells were detected in the COVID-19 and Vacc-AMP groups." (PMID 41164857, 2025). "While the overall proportions of T helper cells (Th, CD4+) and cytotoxic lymphocytes (CTL, CD8+) were similar across LC, acute COVID-19, and convalescent groups, deeper T cell profiling revealed compositional differences in minor subpopulations." (PMID 40806391, 2025). "In the acute COVID-19 phase, we observed differences between severe and mild cases, including significantly lower absolute counts of CD3+ T lymphocytes, CD4+ helper T cells, CD8+ cytotoxic T cells, and NK cells in the severe subgroup." (PMID 41157669, 2025). "On the other hand, increased apoptosis of CD4 and CD8 T cells from COVID-19 patients is correlated to increased FasL expression on T cells." (PMID 40236699, 2025).
COVID-19 (continued). "The results of this study demonstrated the predictive significance of CD4+ and CD8+ peripheral blood cells in COVID-19 patients." (PMID 40718799, 2025). "Our integrative analyses, involving single-cell response eQTLs, COVID-19 GWAS, and single-cell multi-omics data of COVID-19 patients, has also revealed potential roles of SLFN5 in CD4 + T cells upon SARS-CoV-2 infection." (PMID 40759647, 2025). "The severity of COVID-19 correlates with age, partly due to reductions in naïve CD8+ and CD4+ T cells." (PMID 41488664, 2025). "The data demonstrated that compared to COVID-19, LTBI/COVID-19 has predominantly CD4+ T cells with high-polarized compacted mitochondria (HCM) at baseline (p<0.0001) and a similar profile is maintained even with stimulus." (PMID 40458413, 2025). "Individuals with severe COVID-19 had higher FASL expression and higher caspase-8 activity in CD4+ and CD8+ T cells." (PMID 39859379, 2025). "Previous studies have shown that PLWH with higher CD4 counts and CD4/CD8 ratios, who effectively controlled their HIV viral load and received mRNA COVID-19 vaccines, exhibit better immune responses." (PMID 40299994, 2025). "In contrast, the lowest frequencies of IFN-γ-producing CD4+ and CD8+ T cells were detected in unvaccinated COVID-19 patients who subsequently developed severe disease (severity scores 3 and 4, mean SFCs < 50) and death (severity score 5, mean SFCs < 25)." (PMID 40894020, 2025). "The frequency of proliferating T cells, both CD8+ and CD4+, was higher in RSV-infected infants (padj < 0.021 compared to controls; padj < 0.064 compared to COVID-19)." (PMID 39877087, 2025). "While we found similar ART prescription rates between COVID-19-vaccinated PLWH and unvaccinated PLWH, vaccinated PLWH had higher CD4+ T cell counts and were more likely to be virally suppressed." (PMID 40432125, 2025). "The results of this study demonstrate that COVID-19 vaccination induces a robust immune response in people living with HIV (PLWHA), even in those with lower CD4+ T lymphocyte counts." (PMID 40266154, 2025). "Follow-up studies have also shown that leukocytes, total lymphocytes, CD4+ T and CD8+ T cells, and the CD4+/CD8+ T-lymphocyte ratio in patients with COVID-19 are decreased compared to normal subjects." (PMID 40988875, 2025). "In the majority of COVID-19-recovering individuals (COVID-19+), larger overall SARS-CoV-2-specific CD4+ and CD8+ T-cell responses were observed with severe disease, yet an increase in polyfunctional CD8+ T cells was noted in mild cases." (PMID 40698364, 2025). "Our study demonstrates the robust immunogenicity of the bivalent COVID-19 vaccine in virologic suppressed PLWH, with a superior response in those with higher CD4 levels." (PMID 40299994, 2025). "The B cell, CD4+, and CD8+ T cell numbers are consistent with previous reports in immunocompetent patients with acute COVID-19." (PMID 40431250, 2025). "In general, the total number of all lymphocyte subsets (CD3+, CD4+, CD8+, and CD19+) increased across all COVID-19 groups after 1 week of hospitalisation." (PMID 40005306, 2025). "There is a strong need for further research to explore the connection between CD4+ and CD8+ levels, as well as the CD4+/CD8+ lymphocyte ratio, with disease severity and outcomes in COVID-19." (PMID 40718799, 2025). "Our study sheds light on the antibody response to a bivalent mRNA COVID-19 vaccine booster among PLWH, specifically comparing those with CD4 T-cell levels ≤200 cells/mm3 (low CD4 group) to those with higher levels (high CD4 group)." (PMID 40299994, 2025). "COVID-19 vaccines effectively induce SARS-CoV-2-specific neutralizing antibodies and CD4+ and CD8+ T cell responses." (PMID 40573938, 2025). "Few studies have examined the functional spike-specific CD4+ and CD8+ T cell responses by evaluating IFN-γ-, IL-2, or TNF-α-producing T cells by flow cytometry in PwMS after the third dose of COVID-19 mRNA-vaccines." (PMID 41246331, 2025).
COVID-19 (continued). "All groups showed a similar amount of activated CD4 and CD8 circulatory cells; however, the COVID-19 participants demonstrated a notably decreased number of the three main categories of circulatory monocytes: classic, intermediate, and non-classic." (PMID 40497938, 2025). "Studies have found that the counts and percentages of CD4+ T and CD8+ T-lymphocytes correlate with the severity of COVID-19 and are predictive of COVID-19 disease severity in patients." (PMID 40988875, 2025). "While CD4+ T cell subpopulation distribution and function were similar across groups, LTBI/COVID-19 and COVID-19 exhibited similar frequencies of CD8+perforin+ and CD8+Granzime B+ T cells." (PMID 40458413, 2025). "By incorporating B cell and CD4 T cell subset cell densities, we observed a distinct clustering between HLN-Controls of non-COVID-19–infected and COVID-19 LD-LNs." (PMID 40924502, 2025). "While COVID-19 hospitalization outcomes have been extensively studied in PWH, the influence of low CD4 cell count on outcomes of COVID-19 has been less clear." (PMID 40779550, 2025). "Investigators have reported that CD4 and CD8 T cells from patients with COVID-19 had expression of multiple inhibitory molecules including PD-1, PD-L1, Tim-3, and CTLA-4, indicative of T cell exhaustion." (PMID 39903535, 2025). "ASA rates were comparable in CD4 and CD8 conventional subsets but higher in Treg cells for both healthy and COVID-19 samples." (PMID 40903640, 2025). "Patients who died during follow-up had significantly lower absolute counts of CD3+ T cells, CD4+ T cells, CD8+ T cells, and NK cells compared to survivors of COVID-19." (PMID 41157669, 2025). "We analysed surface IL-18Rα expression on CD8 T cells, CD4 T cells and monocytes in the blood from 43 hospitalized RSV, COVID-19, influenza A and influenza B patients during their hospital stays, in comparison to IL-18Rα levels detected in healthy individuals." (PMID 41285788, 2025). "The analysis of snRNA-seq-identified lymphocytes showed increased CD4+ to CD8+ T cell ratios, fewer activated NK cells and a weaker cytotoxic profile of CD8 T cells post-vaccination compared to post-COVID-19." (PMID 39994453, 2025). "Virus-specific CD8+ T cell responses were analyzed in INR (CD4+ T cell count < 300 cells/μL) and immunological responders (IR) (CD4+ T cell count > 500 cells/μL), receiving ART, and HIV-uninfected controls following COVID-19 mRNA vaccination and infection." (PMID 41212052, 2025). "Looking at flow cytometry data, we observed that, upon stimulation by SC2-MP, CD4+ T cells displayed an increase in Fas and OX40 expressions as COVID-19 severity increases from asymptomatic to severe (P ≤ 0.05)." (PMID 40378227, 2025). "Short-term immune responses following a primary COVID-19 vaccination series were lower in PWH compared to HIV-negative individuals, particularly in those with a CD4+ T-cell count < 200 cells per μL." (PMID 40388467, 2025). "Higher FAS expression on CD4+ and CD8+ T cells was identified in patients with COVID-19 than in healthy controls." (PMID 39859379, 2025). "We found a strong positive linear correlation between the high magnitude of IFN-γ-producing CD4+ and CD8+ T cells specific to seven out of ten common T cell antigens and the “natural protection” observed in unvaccinated asymptomatic COVID-19 patients." (PMID 40894020, 2025). "One study found that patients with severe COVID-19 had significantly lower numbers of CD3, CD4, and CD8 lymphocytes compared to patients with milder cases." (PMID 40733642, 2025). "TCR sequencing showed that while CD4 and CD8 T-cell populations were depleted in PBMC of both PIMS-TS and COVID-19 patient groups, the diversity and distribution of their TCRβ and TCRɑ repertoires were grossly normal." (PMID 40331338, 2025). "Four weeks after the first booster dose of BNT162b2, both CD4+ and CD8+ T cells responded to COVID-19 antigens (S, S1, and NMO) by secreting IFN-γ." (PMID 41251472, 2025).